TIMM44 (translocase of inner mitochondrial membrane 44)
Diseases named in the same sentence as TIMM44 in open-access papers (continued):
Sharing a sentence is not in itself a finding about the gene and the disease.
bladder cancer (2 papers, 2024 to 2025). "Here, MB-10 treatment or TIMM44 KO disrupted mitochondrial functions in bladder cancer cells, causing mitochondrial depolarization, oxidative stress and ATP reduction." (PMID 38467612, 2024). "TIMM44 mRNA and protein expression is significantly elevated in different human bladder cancer tissues and various bladder cancer cells." (PMID 38467612, 2024). "Contrarily, ectopic overexpression of TIMM44 using a lentiviral construct augmented proliferation and motility of primary bladder cancer cells." (PMID 38467612, 2024). "The TIMM44 blocker, at 25 μM, decreased cell viability in the primary and immortalized bladder cancer cells." (PMID 38467612, 2024). "When combining the blotting results from all twelve groups of tissues, we show that TIMM44 protein upregulation is significant in the bladder cancer tissues." (PMID 38467612, 2024). "Cell proliferation, tested by nuclear EdU incorporation, and in vitro migration were also substantially inhibited after treatment of TIMM44 blocker in the bladder cancer cells." (PMID 38467612, 2024). "Ectopic overexpression of TIMM44 using lentiviral construct augmented bladder cancer cell growth and motility." (PMID 38467612, 2024). "In the present study, we showed that TIMM44 is important for Akt-mTOR activation in bladder cancer cells." (PMID 38467612, 2024). "In vivo, bladder cancer xenograft growth in nude mice was largely suppressed after genetic depletion of TIMM44." (PMID 38467612, 2024). "Since blockade of TIMM44 induces remarkable antitumor activity in bladder cancer cells, we propose that genetic depletion of TIMM44 should mimic MB-10’s activity." (PMID 38467612, 2024). "MB-10 is a TIMM44 blocker, we show that the mitochondrial apoptosis cascade is induced by MB-10 in bladder cancer cells." (PMID 38467612, 2024). "In the present study, we show that the mitochondrial protein TIMM44 is a promising therapeutic target of bladder cancer." (PMID 38467612, 2024). "TIMM44 mRNA and protein expression is significantly elevated in both human bladder cancer tissues and cells." (PMID 38467612, 2024). "TIMM44 is vital for maintaining mitochondrial integrity and functions, we next explored mitochondrial function change in bladder cancer cells." (PMID 38467612, 2024). "Together, targeting overexpressed TIMM44 by MB-10 significantly inhibits bladder cancer cell growth in vitro and in vivo." (PMID 38467612, 2024). "Moreover, TIMM44 protein upregulation was detected in bladder cancer tissues of four representative patients (“T1/T2/T3/T4”), and its expression was relatively low in corresponding normal tissues (“N1/N2/N3/N4”)." (PMID 38467612, 2024). "The TIMM44 blocker also induced apoptosis in other bladder cancer cells." (PMID 38467612, 2024). "We first tested TIMM44 expression in human bladder cancer tissues." (PMID 38467612, 2024). "Since blockage or depletion of TIMM44 led to robust anti-bladder cancer function, we next propose that increasing TIMM44 expression might produce pro-cancerous activity." (PMID 38467612, 2024). "Moreover, genetic depletion of TIMM44 also arrested bladder cancer xenograft growth in nude mice, leading to oxidative stress, ATP reduction and Akt-S6K1 inhibition in xenograft tissues." (PMID 38467612, 2024). "Therefore, TIMM44 overexpression should be important for maintaining hyper-function of mitochondria, promoting bladder cancer growth and progression." (PMID 38467612, 2024). "Thus, TIMM44 is overexpression in both human bladder cancer tissues and cells." (PMID 38467612, 2024). "Importantly, the first-in-class TIMM44 blocker MB-10 potently inhibits bladder cancer cell growth." (PMID 38467612, 2024). "Therefore the mechanism of action of MB-10-induced cytotoxicity in bladder cancer cells may be different from that of IR-58 targeting TIMM44 in colorectal cancer cells." (PMID 38467612, 2024). "Whether TIMM44 is overexpressed in human bladder cancer cells was also examined." (PMID 38467612, 2024).
bladder cancer (continued). "In priBlCa-1 primary bladder cancer cells, Akt-S6K1 phosphorylation was largely decreased by MB-10 treatment or TIMM44 KO." (PMID 38467612, 2024). "In primary bladder cancer cells, Akt-S6K1 phosphorylation was decreased by MB-10 treatment or TIMM44 depletion, but enhanced after ectopic TIMM44 overexpression." (PMID 38467612, 2024). "Genetic depletion of TIMM44, by the CRISPR-Cas9 method, produced robust anti-bladder cancer activity, inhibiting cell viability, proliferation and mobility, and provoking cell death and apoptosis." (PMID 38467612, 2024). "The TIMM44 blocker induced apoptosis and cell cycle arrest in bladder cancer cells, but failed to provoke cytotoxicity in primary bladder epithelial cells." (PMID 38467612, 2024). "Nevertheless, expression and potential functions of TIMM44 in bladder cancer have not extensity studied." (PMID 38467612, 2024). "The TIMM44 blocker also induced apoptosis and cell cycle arrest in bladder cancer cells, yet failed to provoke cytotoxicity in primary bladder epithelial cells." (PMID 38467612, 2024).
colorectal cancer (2 papers, 2022 to 2024). A primary or metastatic malignant neoplasm that affects the colon or rectum. "A recent study showed that targeting TIMM44 by a mitochondria-targeting near-infrared (NIR) fluorophore IR-58 activated autophagy and apoptosis in an mTOR-related manner, thereby inhibiting colorectal cancer growth." (PMID 38467612, 2024).
thyroid carcinoma (2 papers, 2013 to 2022). "Mitochondrial TIMM44 dysfunction, due to genetic variants, could be associated with thyroid carcinoma development." (PMID 36438483, 2022). "Mutations in TIMM44 and NDUFA13 have been reported to be associated with tumorigenesis in the thyroid, and the SLC5A5 gene encodes sodium-iodide symporter protein, whose down-regulation is associated with thyroid carcinomas." (PMID 23724128, 2013).
tumor (7 papers, 2006 to 2025). "The association between DDX49 and the mitochondria-associated protein TIMM44 suggests that DDX49 may indirectly regulate tumor signaling pathways by modulating mitochondrial functions, including energy metabolism and oxidative stress." (PMID 41438987, 2025). "Taken together, these findings demonstrated that TIMM44 exerted a significant promotional effect on tumor cell proliferation." (PMID 41438987, 2025). "A key observation from this assay was that overexpression of TIMM44 in DDX49-knockdown tumor cells led to partial recovery of the previously significantly suppressed AKT phosphorylation level." (PMID 41438987, 2025). "Analyzing tumor tissues showed that TIMM44 mRNA and protein levels were substantially decreased in KO-TIMM44 xenograft tissues, where ATP contents and GSH/GSSG ratio were decreased." (PMID 38467612, 2024). "Analyzing tumor tissue lysates, we found that TIMM44 mRNA and protein expression in intracranial koTIMM44 tumors was depleted." (PMID 36438483, 2022). "Functional analysis was performed in vitro for both changes and although no dramatic loss of function effects were identified for the mutant alleles, subtler effects might still be present that could alter Timm44 function and thus promote oncocytic tumour development." (PMID 17088905, 2006). "However, whether DDX49 influences tumor cell proliferation through TIMM44 remains to be elucidated." (PMID 41438987, 2025). "Several genes involved in mitochondrial pathways, tumour development or thyroid functions mapping to this region were analysed: EDG5; MARCH2; LASS1; CCL25; ANGPL4; TIMM44; ELAVL1; RAB11B; LASS4; ADAMTS10; PIN1; UBL5; GRIM19; (NIS)." (PMID 17088905, 2006).
cancer (6 papers, 2006 to 2025). A tumor composed of atypical neoplastic, often pleomorphic cells that invade other tissues. "In priBlCa-1 primary cancer cells, TIMM44 KO also induced mitochondrial dysfunction and caused mitochondrial oxidative stress." (PMID 38467612, 2024). "We also considered regional-based DNA methylation changes, and observed one potential pan-cancer DMR in the TIMM44 gene, which was also previously linked to cancer." (PMID 26798410, 2016). "As shown, TIMM44 mRNA expression in “T” cancer tissues were over four folds of that in the “N” normal tissues." (PMID 38467612, 2024). "As shown, TIMM44 mRNA expression is substantially elevated in both primary (priBlCa-1/priBlCa-2/priBlCa-3) and T24 immortalized cancer cells, with relative low mRNA expression detected in priBEC-1 bladder epithelial cells." (PMID 38467612, 2024). "Moreover, TIMM44 protein upregulation was observed in the mitochondrial fraction lysates of the primary and immortalized cancer cells, and low expression in priBEC-1 epithelial cells." (PMID 38467612, 2024). "A previous study has reported an essential role of TIMM44 in cancer growth." (PMID 37147302, 2023).
TIMM44 also shares sentences with these, for which no sentence is quoted: oncocytic thyroid carcinoma (2 papers); diabetes (1); dilated cardiomyopathy (1); medullary thyroid carcinoma (1); serous ovarian cancers (1).